SIRT1 (sirtuin 1)
Diseases named in the same sentence as SIRT1 in open-access papers (continued):
Sharing a sentence is not in itself a finding about the gene and the disease.
neurodegenerative disease (continued). "A number of previous studies showed that Sirt1 plays a protective role in neurodegenerative diseases including HD." (PMID 23762270, 2013). "The clinical success of sirtuin activating compounds (STACs) in neurodegenerative diseases relies overwhelmingly on developing new strategies and designing molecules based on the sirtuin chemistry and molecular pathways activated by SIRT1." (PMID 23888142, 2013). "Increased SIRT1 activity has therefore been proposed as a pharmacological target for the treatment of various degenerative diseases, in particular the age-related vascular, respiratory, hepatic, and renal disorders." (PMID 22848760, 2012). "SIRT1, the mammalian ortholog of SIR2, is induced by CR in multiple tissues of mammals, and has been shown to ameliorate degenerative diseases associated with aging, such as neurodegeneration and metabolic decline." (PMID 18414679, 2008). "By targeting Sirt-1, these compounds could potentially offer neuroprotective effects, making them promising candidates for therapeutic interventions in neurodegenerative diseases like PD." (PMID 41494036, 2026). "Thus, modulation of endogenous antioxidant defense mechanism is an integral method to reduce oxidative stress and improve cell stress response in neurodegenerative diseases by increasing the expression of SIRT1 and Nrf2." (PMID 40379890, 2025). "Furthermore, metformin improves mitophagy in neurodegenerative diseases by activating neuronal SIRT1 signaling." (PMID 40172524, 2025). "Hence, the SIRT1/AMPK axis is increasingly being considered as a potential therapeutic target in neurodegenerative diseases where autophagy and mitophagy are dysfunctional." (PMID 40137124, 2025). "Metformin improves mitophagy in neurodegenerative diseases by activating neuronal SIRT1 signaling." (PMID 40172524, 2025). "However, the complex etiology and progressive nature of neurodegenerative diseases pose significant challenges for the development of effective therapies targeting SIRT1." (PMID 38745862, 2024). "Increasing SIRT1 activity has been shown to be neuroprotective, and strategies to elevate SIRT1 protein levels or boost SIRT1 activity are considered potential interventions for aging and neurodegenerative diseases." (PMID 37253984, 2024). "RSV is known for increasing SIRT1 activity and protecting against oxidative damage in various neurodegenerative disease models, but whether there is a direct interaction between SIRT1 and RSV is still controversial." (PMID 38397799, 2024). "In summary, our study revealed that the AD-associated pathogenic protein Aβ accelerated cellular senescence in human NSCs via SIRT1 inhibition, providing a hopeful target for anti-aging in neural stem cells and the treatment of age-related neurodegenerative diseases." (PMID 38397428, 2024). "The levels of Sirt1 protein were found to be significantly reduced in patients with neurodegenerative diseases compared to those undergoing normal aging, suggesting that diminished Sirt1 expression and activity contribute to the pathological progression of these conditions." (PMID 37622049, 2023). "There is growing evidence that modulation of SIRT1 activity by pharmacological induction or transgenic overexpression may be of therapeutic value in various forms of neurodegenerative diseases." (PMID 36949521, 2023). "There is growing interest that modulation of SIRT1 activity by pharmacological induction or transgenic overexpression may be of therapeutic value in various neurodegenerative diseases." (PMID 36949521, 2023). "Therefore, while a lot more knowledge is required concerning the role of miR‐543 and SIRT1 in PD and other neurodegenerative diseases, both can be considered potential neuroprotective therapeutic targets." (PMID 36352829, 2023). "Recent literatures reported that resveratrol could inhibit oxidation and apoptosis in neurodegenerative diseases through the Nrf2/HO-1, SIRT1, RAX/P-PKR, and JAK2/STAT3/PI3K/AKT/mTOR signaling pathways." (PMID 36836502, 2023).
neurodegenerative disease (continued). "However, during aging, metabolic disorder, or neurodegenerative diseases, the expression of SIRT1 is diminished, intensifying oxidative stress potentially." (PMID 36035216, 2022). "Activating SIRT1 and other sirtuins may also protect neurons in experimental models of neurodegenerative diseases, according to a growing body of research." (PMID 35893883, 2022). "In summary, aspirin may be a potential drug in aging-related neurodegenerative diseases through the SIRT1 pathway." (PMID 36035216, 2022). "SIRT1 stimulated and activated by Taurine also can alleviate the mitochondrial dysfunction induced by amyloid β 1–42 in SK-N-SH cells which provides a suggestion for the diet list of patients with neurodegenerative diseases." (PMID 34616289, 2021). "Sirtuin1 (SIRT1) is an important functional protein in various mammalian metabolic tissues and can regulate the biological processes involved in neurodegenerative diseases, such as inflammation, oxidative stress, mitochondrial function, cell senescence, and apoptosis." (PMID 34336115, 2021). "SIRT1 expression is an important modulator of neurodegenerative disease progression." (PMID 32727328, 2021). "SIRT1 exhibits significant capabilities to enhance neurogenesis and cellular lifespan by regulating various pathways, which makes it an exciting therapeutic target to inhibit neurodegenerative disease progression." (PMID 32727328, 2021). "The decrease in serum SIRT1 protein level was more significant in patients with neurodegenerative diseases than in normal aging individuals, these results indicate the decreased expression and activity of SIRT1 are involved in the pathological process of neurodegenerative diseases." (PMID 34616289, 2021). "It has been demonstrated that activation (overexpression) of SIRT1 may increase lifespan and have an alleviating role in all age-related processes (hallmarks) and several diseases, such as neurodegenerative diseases." (PMID 34206738, 2021). "Moreover, SIRT1 plays important roles in inhibiting the occurrence and development of neurodegenerative diseases, protecting nerve cells, and maintaining normal nerve function." (PMID 34336115, 2021). "Evidence has shown that resveratrol, a potent SIRT1 activator, is a powerful neuroprotective agent and may play a role in the treatment of neurodegenerative diseases." (PMID 32148659, 2020). "Overall, our data suggest HYA, a novel SIRT1 activator, could serve as an effective approach to treat LPS-induced neurodegenerative diseases." (PMID 33041785, 2020). "Moreover, SIRT1 exerts neuroprotective effects in many models of microglial activation-induced neurodegenerative disease." (PMID 32802267, 2020). "Furthermore, resveratrol afforded neuroprotection in multiple pathways dependent on activating SIRT1 in neurodegenerative diseases." (PMID 33381265, 2020). "For a long time, SIRT-1 has been considered to be correlated with neural development and antiaging in mammals, offering significant potential as an effective treatment strategy for neurodegenerative diseases." (PMID 32831997, 2020). "Thus, our research identifies SIRT-1 as a potent therapeutic target and H2S as a potent treatment for Hcy-related neurodegenerative diseases." (PMID 32132865, 2020). "Interestingly, due to important effects on metabolism and physiological activities in CNS, SIRT1 has attracted great attention as medicinal targets particularly on neurodegenerative diseases." (PMID 33198798, 2020). "It has been reported that Sirt1 has the neuroprotective effect in neurodegenerative diseases, which could depend on its function in lengthening cell lifespan and bolstering cell viability." (PMID 30426321, 2019). "Thus, enhancing SIRT1 expression and its activity has clearly revealed it to be an attractive therapeutic approach for neurodegenerative disease." (PMID 30973934, 2019).
neurodegenerative disease (continued). "Based on neuroprotection by SIRT1 in cell culture and in vivo models of neurodegenerative disease it has been suggested that elevating SIRT1 activity could have benefits in neurodegenerative diseases." (PMID 30973934, 2019). "The role of SIRT1 in animal models of neurodegenerative diseases." (PMID 30416425, 2018). "Another neurodegenerative disease in which SIRT1 has been investigated is HD." (PMID 30532738, 2018). "Present literature indicates that acute phase proteins, e.g., plasma Sirtuin 1, could contribute information in order to quantify neuronal damage in neurodegenerative diseases." (PMID 29976874, 2018). "Given the importance of this deacetylase activity of Sirt1 in HD, our results suggest that βL may increase Sirt1 and modify HD and other neurodegenerative diseases." (PMID 29742127, 2018). "Moreover, this compound can also modulate different molecular pathways dependent on silent information regulator-1 (SIRT1) in neurodegenerative diseases." (PMID 30510627, 2018). "Silent information regulator 1 (SIRT1) exerts neuroprotection in many neurodegenerative diseases." (PMID 29375306, 2017). "Our studies suggest SIRT1/PGC-1α as underlying pathways contributing to AMD pathophysiology, and open new avenues for development of targeted drugs for treatment of this devastating neurodegenerative disease of the visual system." (PMID 27998274, 2016). "Because javamide-II was a stronger inhibitor for Sirt2 than Sirt1, that could be more relevant to neurodegenerative diseases." (PMID 26986569, 2016). "SIRT1 is an important protective factor against neurodegenerative diseases in humans." (PMID 27203679, 2016). "The beneficial role of SIRT1 has been demonstrated in various neurodegenerative disease models." (PMID 25167838, 2014). "The common mechanism of oxidative stress found in many neurodegenerative processes suggests that SIRT1 activators may exert similar anti-oxidative effects as potential neuroprotectants in a variety of neurodegenerative diseases." (PMID 23293585, 2012). "Furthermore, oxidative stress and mitochondrial dysfunction may induce AD neuropathology indirectly by reducing the expression of the neuroprotective SIRT1 which improve neurogenesis and reduce neuroinflammation in different neurodegenerative diseases." (PMID 39644152, 2024). "SIRT1 is primarily expressed in neurons and in the adult brain, with high levels in the cortex, hippocampus, cerebellum and hypothalamus, besides, SIRT1 is the most extensively studied sirtuin in the context of neurodegenerative diseases such as AD, PD, and HD." (PMID 36237161, 2023). "In summary, Sirt1 may play a crucial role in neurodegenerative diseases." (PMID 37622049, 2023). "Thus, targeting the SIRT1/NRF2 pathway could be a potential strategy for combating neurodegenerative diseases related to aging." (PMID 38132144, 2023). "Neurodegenerative diseases treatment may benefit from SIRT-1 inhibitors as well as activators." (PMID 36080416, 2022). "Therefore, regulation of the SIRT1/NRF2 pathway may provide a hopeful way for preventing or treating aging-related neurodegenerative disease." (PMID 36035216, 2022). "Consequently, PARP1 inhibition can alleviate neuroinflammation, dysregulation of autophagy and mitochondrial dysfunction thereby inhibit development of inflammation(age)-related neurodegenerative diseases (or alleviate their symptoms), for example via SIRT1 activation." (PMID 34206738, 2021). "Thus, pharmacological activation or upregulation of SIRT1 may be a promising strategy for the treatment of inflammation-related neurodegenerative diseases." (PMID 32802267, 2020). "SIRT1 (Sirtuin 1), also called the silent information regulator 2 protein, belongs to the sirtuin family of class III histone deacetylases (HDAC) and has recently been implicated in age-related diseases, including metabolic, cardiovascular, and neurodegenerative diseases." (PMID 33021962, 2020).
neurodegenerative disease (continued). "Thus, cannabisin F may be a potential therapeutic agent for treatment of neurodegenerative diseases as modulators of SIRT1/NF-κB and Nrf2." (PMID 30691004, 2019). "Because the SIRT1 gene is highly related to aging and neurodegenerative diseases, we also hypothesize that the expression of the SIRT1 gene, which is directly regulated by miR-34a, along with the SIRT1 downstream genes would be positively activated after complete treatment for BPPV." (PMID 27203679, 2016). "As reduced NAD(H) levels impact at least PARP and SIRT1 activity the observed decrease in NAD(H) availability within the aging brain may facilitate cell metabolic and genomic instability increasing an individuals’ susceptibility to degenerative disease." (PMID 24454842, 2014). "SIRT1 activators such as resveratrol, SRT1720, and SRT2104 have been shown to alleviate neurodegenerative disease symptoms by reducing oxidative stress, enhancing autophagy flux, and promoting neuronal survival." (PMID 40109363, 2025). "Our findings demonstrate that RSV alleviates motor dysfunction in PD by inhibiting ferroptosis through SIRT1/NRF2 activation, providing novel mechanistic insights into its therapeutic potential for neurodegenerative diseases." (PMID 41220093, 2025). "Similarly, SIRT1 is a nicotinamide adenine dinucleotide-dependent histone deacetylase, which imparts a fundamental role in neuroprotection through abolishing multiple factors involved in neuronal death in neurodegenerative diseases, such as oxidative stress and neuroinflammation." (PMID 38112964, 2024). "Sirtuin 1 (SIRT1) is a NAD+-dependent deacetylase that regulates neuronal mitochondrial biogenesis and quality control in neurodegenerative diseases via deacetylation of a variety of substrates." (PMID 39273653, 2024). "SIRT1, a homologue of SIR2, has been shown to have neuroprotective effects in central neurodegenerative diseases." (PMID 38783169, 2024). "Despite the neuroprotective potential of RSV as a SIRT1 activator and PARP1 inhibitor, the low oral bioavailability of this polyphenol has limited its use as an effective drug to treat neurodegenerative diseases." (PMID 38397799, 2024). "SIRT1/AMPK activity has been shown to play a key role in autophagy by inducing mitochondrial fragmentation, which serves a neuroprotective role in slowing neurodegenerative disease progression." (PMID 37456463, 2023). "While the neuroprotection of SIRT1 activation and SIRT2 inhibition have been reported, the common substrates of SIRT1 and SIRT2 and their cooperative effects in neurodegenerative disease have been less established." (PMID 37602729, 2023). "In neurodegenerative diseases, RES was shown to exert a neuroprotective effect through the aggregation of the SIRT1 signaling pathway." (PMID 34247566, 2022). "In the aging-related neurodegenerative diseases, the AMPK/SIRT1 signaling pathway acts as a crucial role in regulating energy metabolism, apoptosis as well as neuroinflammation." (PMID 34630111, 2021). "Specific overexpression of certain proteins such as SIRT1, BIP, and/or ATG5 facilitates neuronal survival after nerve injury, and they neuroprotect in neurodegenerative diseases." (PMID 33578870, 2021). "SIRT1 and SIRT2 can have opposing effects in promoting angiogenesis and in providing neuroprotective effects in neurodegenerative disease models." (PMID 33059738, 2020). "SIRT1, a NAD+-dependent deacetylase, protects neurons in a variety of in vitro and in vivo models of neurodegenerative disease." (PMID 30973934, 2019). "This review describes the dysfunctions of mitochondria in aging and neurodegenerative diseases, and the signaling pathways leading to mitochondrial biogenesis (including PGC‐1 family proteins, SIRT1, AMPK) and mitophagy (parkin‐Pink1 pathway)." (PMID 30889315, 2019). "Both SIRT1 activation and SIRT2 inhibition have been identified as good strategies for neurodegenerative diseases." (PMID 29748539, 2018).
neurodegenerative disease (continued). "SIRT1 and NRF2 stimulate anti-inflammatory mechanisms and have previously demonstrated therapeutic value in preclinical models of neurodegenerative disease." (PMID 29494741, 2018). "Both the silent mating type information (Sirt1) expression and mitogen-activated protein kinase (MAPK) signal pathway activation represent a promising therapeutic target for several models of neurodegenerative diseases." (PMID 28356158, 2017). "Importantly, SIRT1 activity is enhanced by small-molecule compounds; it may, therefore, be critically important to develop sirtuin activators tailored to cross the blood brain barrier to treat neurodegenerative diseases." (PMID 23251824, 2012). "Our findings on the interaction between SIRT1 and MICU1 raise the question of whether SIRT1 exerts its protective effects in various neurodegenerative diseases through this pathway." (PMID 40003583, 2025). "SIRT1 level is decreased in aging, AD, and other neurodegenerative diseases, and tau is hyperacetylated in the absence of SIRT1, causing acetylated (and also phosphorylated) tau to accumulate." (PMID 39596399, 2024). "SIRT1 is a (NAD+)-dependent deacetylases that modulate multiple cellular processes, and has reported neuroprotective role in several neurodegenerative diseases and psychiatric disorders." (PMID 36437988, 2022). "This SIRT1 effect could bolster the therapeutic usefulness of AAV-mediated SIRT1 expression for the treatment of demyelinating and neurodegenerative diseases at large." (PMID 35740955, 2022). "There is compelling evidence to support regulation of SIRT1 and SIRT2 that are shuttled between the nucleus and cytoplasm and their inhibition might be beneficial in neurodegenerative diseases, including HD." (PMID 36557263, 2022). "Another neurodegenerative disease to be noted is ALS, for which the inhibitor EX-527 has shown a neuroprotective effect in an in vitro study, by increasing neuron viability, although with an action independent from SIRT-1 inhibition." (PMID 36080416, 2022). "Furthermore, activation of SIRT1 with resveratrol, a natural polyphenol agonist of SIRT1, mitigated neuronal injury by regulating the expression of BDNF in animal models of neurodegenerative diseases." (PMID 32148659, 2020). "This study explores the various modulators that regulate the activity of SIRT1 and SIRT2, which may further assist in the treatment of neurodegenerative disease." (PMID 33597872, 2020). "Manipulating activities of SIRT1 and SIRT2 show the opposing effects in neurodegenerative disease." (PMID 31214610, 2019). "Accordingly, the mechanisms by which RVTL may promote neuroplasticity are unknown; however, recent studies have proposed that AMP-activated protein kinase and Sirt-1 have beneficial participation on RVTL in neurodegenerative diseases models." (PMID 26695764, 2015). "Here, we review the potential roles and effects of SIRT1 and SIRT2 in neurodegenerative diseases." (PMID 23417962, 2013). "SIRT1-activating compounds have not yet been proven to be clinically useful for the treatment of neurodegenerative diseases." (PMID 23888142, 2013). "Given the complexity of the interactions between PPARγ, SIRT1, and AMPK, further investigations are necessary to elucidate the precise pathways through which QUR activates PPARγ and to determine its potential therapeutic applications in neurodegenerative diseases." (PMID 40430476, 2025). "Therefore, activating the SIRT1/NRF2 pathway may provide a promising way for prevention and treatment of aging-related neurodegenerative diseases." (PMID 36035216, 2022). "However, there have also been reports in several animal models of neurodegenerative diseases that SIRT1 activation does not have neuroprotective effects." (PMID 30416425, 2018). "Resveratrol is a nonflavonoid polyphenol that acts in various neurodegenerative diseases by activating metabolic sensor/effector proteins, including AMP-activated protein kinase (AMPK), sirtuin 1 (SIRT1), and PGC-1α." (PMID 36009443, 2022).